Y_RNA (Y RNA )
Gene: Miscellaneous RNA gene on chromosome 1 (93,027,410 to 93,027,506, reverse strand). Ensembl gene ENSG00000251837.
Homologues: Orthologues: chimpanzee Y_RNA (100% identical), pig Y_RNA (87% identical), dog Y_RNA (84% identical), macaque Y_RNA (80% identical). Paralogues in human: Y_RNA (89% identical), Y_RNA (88% identical), RNY3 (87% identical), RNY3P1 (87% identical), Y_RNA (87% identical), Y_RNA (86% identical), RNY3P14 (85% identical), RNY3P4 (85% identical), Y_RNA (85% identical), RNY3P16 (84% identical), Y_RNA (84% identical), Y_RNA (82% identical), and 94 more.